MYC (MYC proto-oncogene, bHLH transcription factor)
Diseases named in the same sentence as MYC in open-access papers (continued):
Sharing a sentence is not in itself a finding about the gene and the disease.
cancer (continued). "Many human cancers including GBMs demonstrate addiction to MYC transcription factor signaling and can become susceptible to inhibition of MYC downstream genes." (PMID 31754113, 2019). "Future studies will likely broaden the repertoire of lncRNAs regulating MYC and improve the understanding of the underlying mechanisms in normal and cancer cells." (PMID 30451365, 2019). "Since activation of c-MYC has been observed in SMARCB1-deficient cancers, we assessed how c-MYC levels are altered upon proteasome inhibition." (PMID 30860482, 2019). "MYC is one of the most frequently deregulated oncogenes in many cancer types and a hallmark of the majority of human cancers." (PMID 31058089, 2019). "CircPVT1 derives from PVT1 gene, which resides close to MYC in 8q24, identified as a risk locus of many cancers including leukemia." (PMID 31605010, 2019). "We also found that the hub genes (e.g., MAPK8, EGF, FALGDS, CCND1, MYC) in this network have been linked to cancer in wide literature reports." (PMID 31080457, 2019). "Elevated or deregulated expression of c-MYC has been detected in various human cancers and is frequently associated with aggressive and poorly differentiated tumors." (PMID 30875980, 2019). "Because MYC deregulation is observed in multiple human cancers and associated with poor prognoses, there have been intense research efforts to develop treatments that target MYC21." (PMID 31848373, 2019). "High levels of the MYC protein allow tumour initiation, progression and maintenance, which is associated with Burkitt’s lymphoma (BL), among other cancer diseases." (PMID 30871121, 2019). "High MYC expression drives tumor initiation, progression, and maintenance and is associated with aggressive cancers and poor prognoses." (PMID 31196146, 2019). "This is consistent with the ability of MYC to drive cell cycle progression, a phenotypic hallmark of cancer." (PMID 30902071, 2019). "PVT1 is located downstream of proto-oncogene MYC on chromosomal region 8q24, a known cancer susceptibility locus." (PMID 31508377, 2019). "Further, SIRT6 deficiency is linked to increased ribosome biogenesis in cancer cells driven by the de-repression of the MYC transcription factor." (PMID 31372634, 2019). "The MYC gene encodes a human transcription factor and proto-oncogene that is dysregulated in over half of all known cancers." (PMID 31206539, 2019). "The most commonly occurring cancer mutations, including oncogenes such as MYC, Ras and PIK3C, are found in signal transductions pathways feeding into the translational machinery." (PMID 31118010, 2019). "MYC family of genes is known to cause cancer by an overexpression of the product protein, c-MYC, for some reason combined with a loss of the original function of cell cycle control." (PMID 35582594, 2019). "MXD1 is a MYC inhibitor and competes with MAX, a co-activator, with this MYC/MXD1/MAX signaling pathway being implicated in the development of some types of cancer." (PMID 31261609, 2019). "MYC is also a potent oncogene and is frequently overexpressed in human cancers, leading to many of the hallmarks associated with tumorigenesis, including autonomous proliferation, increased biogenesis and altered metabolism." (PMID 31455158, 2019). "The previous studies demonstrated a significant contribution of NC_000008.10:g.128413305 G>T (rs6983267) single-nucleotide polymorphism (SNP) in the MYC enhancer region to the susceptibility to various cancers." (PMID 29525942, 2018). "Studies in other cancers have shown that disease-specific risk loci at 8q24.21 lie within tissue-specific enhancers interacting with MYC or PVT1 promotors." (PMID 29632299, 2018).
cancer (continued). "RNA-Seq analysis of the prostate cancer transcriptome identified 121 unannotated ncRNA transcripts, of which PCAT-1 (prostate cancer-associated transcript 1) is a sense lncRNA localized upstream of the MYC gene at the 8q24 genomic region." (PMID 29739426, 2018). "First, although MYC is involved in regulating cancer metabolism, the detailed metabolic changes caused by metformin have not been determined in the current study." (PMID 30221473, 2018). "MYC expression is closely associated with the progression of cell-cycle in normal tissues and its overexpression has been found in variety of cancer types." (PMID 29444163, 2018). "Recent evidence suggests that metabolic changes, caused by oncogenic activation of signal transduction pathways and transcription factors such as MYC, satisfy the large biosynthetic requirements associated with cancer cell proliferation." (PMID 29789716, 2018). "When we compared AS events commonly modulated by T‐025 in the four cancer cell lines with MYC‐dependent AS events, only five of the 546 events (|ΔPSI| > 0.2) associated with T‐025 treatment were observed among MYC‐dependent AS events." (PMID 29769258, 2018). "Recent reports that spliceosome inhibition is more effective against MYC‐driven cancer persuaded us to validate this preliminary analysis result that MYC‐mutated or MYC‐amplified cancer cell lines were more sensitive." (PMID 29769258, 2018). "In a study using a very different approach published during the preparation of this manuscript, MYC was also implicated in pathways involving activated FGFRs in several different types of cancer." (PMID 29463565, 2018). "In other cancers such as medulloblastoma, however, Wnt pathway activation is associated with a more favourable clinical subtype distinct from the more aggressive c-MYC driven subtype." (PMID 29505958, 2018). "Among them, the MYC pathway/targets are prominent gene sets enriched with EPIC1-associated genes in both cancer cell lines and EPIC1-knockdown cells." (PMID 30093685, 2018). "Overexpression of MYC in cancer cells cause upregulation of many genes including glycolytic enzymes, PDK1, lactate dehydrogenase, and glucose transporters." (PMID 29495398, 2018). "DM chromosomes have a predisposition to involve cancer oncogenes such as MYC proto-oncogene protein (MYC), MDM2 proto-oncogene (MDM2) or cyclin-dependent kinase 4 (CDK4)." (PMID 29616301, 2018). "We also observed that the rs6983267 G variant was associated with increased MYC transcript levels and enhanced growth and spread of cancer cells to neighboring tissues." (PMID 29525942, 2018). "Previous studies have reported a significant contribution of NC_000008.10:g.128413305 G>T (rs6983267) single-nucleotide polymorphism (SNP) in the MYC enhancer region to the susceptibility of various cancers." (PMID 29525942, 2018). "We identified a sub-network with a high number of shared, targeting miRNAs, of genes associated with cellular proliferation and cancer, including c-MYC and Cyclin D." (PMID 29329594, 2018). "Activation of the MYC gene, which encodes c-MYC, is a hallmark of cancer initiation and maintenance." (PMID 29641996, 2018). "Consistently, MYC is associated with the invasion and metastasis potential of multiple types of cancer cells, and it can be upregulated by ANXA2." (PMID 30081903, 2018). "MYC was upregulated in carcinoma tissue (FC 3.70) and was associated with both hsa-miR-17-5p and hsa-miR-20a-5p with positive beta coefficients, without identified seed matches." (PMID 29725503, 2018). "Until recently, there has been a general consensus that MYC plays a key role in the development of many human cancers, even though enhanced cell growth caused by MYC is countered by higher rates of apoptosis." (PMID 28152508, 2017). "This gene lies within the 8q24 ‘gene desert’ hotspot that is home to the MYC oncogene and is associated with numerous cancers, highlighting the significance of lncRNAs in genetic predisposition to cancer." (PMID 29113413, 2017).
cancer (continued). "Further systems biology analyses revealed that this miRNA signature impacted oncogenic factors related to JUN and MYC and other important functions associated with cancer cell growth." (PMID 28107482, 2017). "In liver cells, treatment with As2O3 correlated with hypomethylation in the cis-regulatory sites of the promoter of MYC (a known cancer-associated gene), as well as hypermethylation in the promoter of MAX (a regulator of MYC and cell cycle)." (PMID 28179585, 2017). "Last, many molecules associated with general cancer mechanisms were regulated including bcatenin, HIF1α, MYC or aurora kinase A." (PMID 29299138, 2017). "As such, MYC overexpression is a characteristic hallmark of a broad spectrum of cancers and can directly lead to malignant transformation in several cancer types." (PMID 28245597, 2017). "The gene desert upstream of the MYC oncogene on chromosome 8q24 contains susceptibility loci for several major forms of human cancer." (PMID 28583252, 2017). "Despite the fact that these strategies can cause off-target effects, some have yielded highly promising results and are tested in clinical trials, paving the road for epigenetic drugs to treat MYC-associated human cancers." (PMID 28505071, 2017). "Variants in the MYC upstream region contribute to inherited susceptibility to most major forms of human cancer, and account for a very large number of cancer cases at the population level." (PMID 28583252, 2017). "Downregulation of MYC mRNA and protein expression in multiple cancer cell lines is caused by inhibition of PRKDC, which leads to over-expression of MYC family of proteins induced DNA double-strand breaks and leads to cancer progression." (PMID 28871116, 2017). "A number of HDAC inhibitors are currently in clinical trials and are probably the most encouraging of the emerging epigenetic anti-cancer therapeutics for MYC-associated cancers." (PMID 28505071, 2017). "The region has multiple enhancers for a cancer-linked gene called MYC and is implicated in many cancer-associated deaths every year." (PMID 28583252, 2017). "MYC expression is deregulated in a wide array of cancers and is generally associated with poor prognosis." (PMID 28674522, 2017). "While TR therapies often broadly include the repression of specific cancer driver genes, such as MYC, the underlying molecular bases for any cancer type are fairly heterogeneous as revealed by the cancer genomic and transcriptomic data." (PMID 28454100, 2017). "Altogether these evidences underline the potential of targeting MYC and its modulated targets for cancer therapy." (PMID 28217689, 2017). "The oncoprotein MYC is a master regulator of many cellular signaling and metabolic pathways and has been implicated in drug resistance in breast cancer by allowing cancer cells to reprogram under specific drug induced stress." (PMID 28696357, 2017). "It is undoubtedly envisioned that the failure of stringent regulation of MYC activity is associated with aberrant growth behaviors leading to the development of cancer stemness." (PMID 28590415, 2017). "PVT1 is a potential oncogene that has been implicated in a variety of cancers, participating in DNA rearrangements, interacting with MYC and encoding miRNAs." (PMID 29242407, 2017). "The MYC oncogene encodes for a transcription factor that is overexpressed in multiple human cancer types, including NSCLC." (PMID 29050242, 2017). "In this review, we summarize the underlying mechanisms of the conflicting functions of MYC in genomic instability and discuss when and how the oncoprotein exerts the contradictory roles in induction of DSBs and protection of cancer-cell genomes." (PMID 28590415, 2017). "For example, multiple SNPs linked to a number of cancers map to a gene desert surrounding the oncogene MYC at the 8q24 locus." (PMID 28529100, 2017). "MYC, which has known oncogenic effects in various cancers, induces nuclear-encoded mitochondrial gene expression and mitochondrial biogenesis in cancer." (PMID 28373964, 2017).
cancer (continued). "Many human cancers appear to be associated with or even strictly dependent on activated MYC signaling (reviewed in ref.25)." (PMID 29180625, 2017). "Overlapping Linear Motifs (OLPs) found in the cancer-associated hub proteins (CPs) MYC, APC and MDM2." (PMID 27218803, 2016). "MYC proteins therefore belong to those crucial master switches in most human cancers, from which many of them are associated with a poor clinical outcome." (PMID 27313991, 2016). "These evolutionary traits of transient polyploidy linked to embryonalisation and exploiting c-MYC likely became usurped by cancer cells conferring them resistance to treatments coupled with proliferative and metastatic potential." (PMID 27655693, 2016). "But experiments have shown that changes in the expression of some master regulators such as c-MYC can cause global shift in the expression of almost all genes in some cell types like cancers." (PMID 27092944, 2016). "qRT-PCR was performed to verify GEP findings and analyze the relationship between copy number change and expression change in four well known cancer associated genes including MYC, KIT, FLT3, and PTEN." (PMID 27639374, 2016). "For example, MYC, a well-known hallmark of aggressive cancers, was validated by qPCR to follow the same pattern of differential gene expression as xCT in MDA-MB-231 and T47D SH-4-54-resistant clones relative to their respective wild-type counterparts." (PMID 27513743, 2016). "c-Myc expression has also been associated with platinum resistance in various cancer types for example via repression of c-MYC inhibitor bridging integrator 1 or increased platinum accumulation in cells." (PMID 27191653, 2016). "This dual role of MYC as a driver of Warburg effect and a promoter of mitochondrial biogenesis underlies the dependence of cancer cells on glutamine oxidation, an essential event for cell survival under conditions with low glucose and oxygen." (PMID 27455839, 2016). "74.29% of the high-risk patients carried MYC amplification which can lead to poor prognosis via enhancing cell cycle and proliferation of cancer cell." (PMID 27006471, 2016). "In this work, PPI data and de novo motif identification based method (MEME) were used to identify such peptides in three cancer-associated hub proteins—MYC, APC and MDM2." (PMID 27218803, 2016). "Elevated MYC proteins are associated with many cancers and correlate with cancer risk and poor patient survival." (PMID 27472461, 2016). "The dependence of cancer on overexpressed c-MYC and its predisposition for polyploidy represents a double puzzle." (PMID 27655693, 2016). "MYC is often amplified and/or mutated in cancer, especially in the prostate where it can play a role as an oncogene." (PMID 27611945, 2016). "Efficacy of BET inhibitors in cell proliferation has been linked to the transcriptional downregulation of c-MYC in several different cancer models." (PMID 27259267, 2016). "Constitutive activation of MYC leads to neoplastic cell transformation, and deregulated MYC alleles are frequently observed in many human cancer cell types." (PMID 27313991, 2016). "MYC has been implicated to drive the expression of glycolytic genes in cancer cells, thus the GSCA finding of these cancer cell lines for high MYC and high glycolysis is consistent with existing literature." (PMID 26350211, 2016). "Because of this compensatory mechanism, our data demonstrate that the simultaneous inhibition of both CDK9's catalytic activity and MYC's expression or function causes synergistic induction of growth arrest and apoptosis of cancer cells." (PMID 26083714, 2015).